CCL5 (C-C motif chemokine ligand 5)
Diseases named in the same sentence as CCL5 in open-access papers (continued):
Sharing a sentence is not in itself a finding about the gene and the disease.
COVID-19 (continued). "Significant upregulation of tumor necrosis factor-α (TNF-α), interleukin-6 (IL-6), and C–C motif chemokine ligand 5 (CCL5) was observed from exposure of immortalized human hepatocytes (IHHs) to exosomes isolated from COVID-19 patient plasma compared with exosomes from healthy normal plasma." (PMID 33804769, 2021). "Therefore, early intervention to prevent overexpression of CCL5 can restore immune balance in COVID-19 patients and prevent disease progression." (PMID 34975885, 2021). "The peripheral blood levels of CCL5 were elevated before IL-6 in severe COVID-19 patients." (PMID 32766256, 2020). "This study highlights the associations of the IL-6 rs1800796 (-572 G/C), IL-10 rs1800871 (-819 C/T), rs1800872 (-592 C/A) and CCL5 rs2107538 polymorphisms with fatal COVID-19 outcomes and elevation of cytokines (CCL-2, IL-6, IL-10 and CXC-L10) plays a crucial role in the pathogenesis of COVID-19." (PMID 40881695, 2025). "Moreover, a gene expression study on peripheral blood samples showed that the increase in CCL5 in the early stage of the infection might prevent severe COVID-19." (PMID 39590591, 2024). "Furthermore, decreased expression of CCL5 and elevated viral load of severe acute respiratory syndrome-coronavirus-2 (SARS-CoV-2) in nasopharyngeal samples were associated with poor outcomes of coronavirus disease 2019 (COVID-19)." (PMID 39431236, 2024). "Furthermore, ARDS caused by COVID-19 differed from non-COVID-19 ARDS in that the former generated an increased expression of CCL5/RANTES while reducing IL-2, TNF-related apoptosis-inducing ligand (TRAIL), and granulocyte-colony-stimulating factor (G-CSF)." (PMID 36851766, 2023). "Importantly, elevation of IL-6 levels in severe COVID-19 patients was later than that of CCL5." (PMID 32766256, 2020). "Six chemokines (CXCL9, CXCL10, CCL4, CCL5, CCL27, and CXCL12) and eight interleukins (IL-1Ra, IL-2Ra, IL-3, IL-5, IL-9, IL-12p40, IL-15, and IL-16) were increased in both PLWH/COVID-19 and COVID-19-only." (PMID 41516165, 2025). "Supervised machine learning algorithm (RF) was used to predict the COVID-19 severity and chronicity based on immune subset profiling and a 14-plex cytokine panel (TNF-a, IL-4, IL-13, IL-2, GM-CSF, sCD40L, CCL5, CCL3, IL-6, IL-10, IFN-g, VEGF, IL-8, and CCL4." (PMID 40657638, 2025). "Lastly, C3, CXCL11, and CCL5 are established immune proteins that were elevated in our MIS-C cohort and have been previously identified to be elevated in COVID-19 patients." (PMID 38632526, 2024). "The main inflammatory cytokines and chemokines widely produced by patients with severe forms of COVID-19 are IL-6, IL-8, IL-1β, TNF-alpha, IFN-gamma, MIP1α and 1β, CCL2, CCL5, CCL20, CXCL1, CXCL2, CXCL8, CXCL10, and CXCL17." (PMID 39768136, 2024). "In the present study, the differential expression of seven genes related to immunity, IRF9, CCL5, IFI6, TGFB1, IL1B, OAS1, and TFRC, was analyzed in individuals with COVID-19 diagnoses of different disease severities." (PMID 38731851, 2024). "In one study, it was noted that the activation of the innate immune system and cytokine storms (featuring elevated levels of TNF, IL-6, CXCL10, CCL2, CCL5, and IFN2) play crucial roles in the pathogenesis of COVID-19." (PMID 39685844, 2024). "Based on relevant results reported in the existing literature and a previous study of our group, the genes CCL5, OAS1, IRF9, IFI6, TGFB1, IL1B, and TFRC were analyzed in the present study in relation to the severity of COVID-19." (PMID 38731851, 2024). "CCL3, CCL5, CXCL2, and CXCL10 have been reported to be increased in patients with severe COVID-19-related acute respiratory distress syndrome (ARDS)." (PMID 38584257, 2024). "Both CCL5 and CXCL10 were reported to be predictive biomarkers for clinical outcomes of COVID-19, and it appears this observation can be broadly applied to other betacoronaviruses, including PHEV." (PMID 38932231, 2024).
COVID-19 (continued). "A total of 13/124 measures including CCL5, CCL17, IL-18, IFNα2, Fractalkine, classical monocytes, T cells, and CD4Temra exhibited significant sex differences in female vs. male COVID-19 patients." (PMID 37998327, 2023). "While a protective effect of OAS1, IRF9, and IFI6 in asymptomatic and mild COVID-19 is confirmed, the role of TGFB1 and CCL5 is still controversial." (PMID 37389217, 2023). "In genomic studies, some up-regulated homologous chemokines such as CXCL9, CXCL10 and CCL5, which are involved in the regulation of immune cell migration and activation in IPF, were also detected in COVID-19 patients." (PMID 37391786, 2023). "Alongside, we observed a high expression of cytokines (CCL3, CCL4, CCL5, CCL7, CCL18 and CCL20) in the CD4+ TCM, Classical monocytes and NK cells in the COVID-19 patients." (PMID 36532041, 2022). "In symptomatic or asymptomatic COVID-19, the CCL3, CCL4, and CCL5 chemokines were detected in a similar fashion." (PMID 36016187, 2022). "Compared to NI subjects, COVID-19 patients had significantly elevated levels of IL-6, IL-10, IFN-γ, CCL5, CXCL9, and CXCL10 and decreased levels of CXCL8." (PMID 36287506, 2022). "This framework releases large amounts of pro-inflammatory cytokines, as in COVID-19, including IL-6, TNF, IL-1β, IL-12, IL-17, IL-18, IP-10, IFN-γ, CCL2 and CCL5." (PMID 35843719, 2022). "In a study on COVID-19, CCL4 was highly expressed in the bronchoalveolar lavage fluid of patients, and CCL5 expression was variable." (PMID 36420258, 2022). "COVID-19 patients have been shown to have higher levels of chemokines such as CCL3, CCL5, CXCL10, CCL19, CCL20, while CCL5 remained unchanged." (PMID 35782361, 2022). "Across disease states and accounting for age, CD8+ T effector memory (CD8.TEM/TEMRA), CD8+ T central memory (CD8.TCM/CD8.TCM.CCL5), and MAIT cell diversity were reduced in COVID-19 severe and critical disease with comparable changes in sepsis." (PMID 35216673, 2022). "Several inflammatory cytokines/chemokines were found to be elevated in many COVID-19 patients (e.g., Eotaxin, Gro-α, CXCL-10 (IP-10), RANTES (CCL5), IL-2Rα, MCP-1, and SCGF-b); CXCL-10 was elevated in all." (PMID 34242356, 2021). "Its chemokine ligands CCL-5 (RANTES), CCL-3, CCL-4 (also known as MIP-1α and 1β, respectively), and CCL-3L1 are upregulated in severe COVID-19 cases." (PMID 33445810, 2021). "In a cohort study, plasma MPO-DNA complexes defined as NETs, platelet factor 4, RANTES (CCL5) and selected cytokines were measured in plasma samples from COVID-19 patients (n = 33) and age- and sex-matched controls (n = 17)." (PMID 34359859, 2021). "Nevertheless, an intense increment of plasmatic levels of IL-6 and CCL5 (also known as RANTES), a ligand for CCR5, decreased CD8 + T cell levels, and SARS-CoV-2 plasma viremia in severe COVID-19 patients." (PMID 34753980, 2021). "The current data suggest that chemokines such as CCL2, CCL3, CCL5, and IP10 are the initiators of the deadly COVID-19 immunopathological pathway." (PMID 32766256, 2020). "Even the higher COVID-19 mortality rate observed in male compared to female patients may correlate with sex differences in the immune responses between male and female, with higher plasma levels cytokines and chemokines including IL-6, IL-8, IL-18, CCL5 found in male patients." (PMID 33362782, 2020). "Based on our results, we suggest that controlling high-severity-specific markers (FOS, CXCL8, HLA-A, JAK3, ICAM1, and H2BC4) and low-severity-specific markers (IL1B, CD3D, CD4, CCL5, and SNRPB) may prevent COVID-19 progression." (PMID 41155463, 2025). "These included IL-6, TNF-α, CCL5, and CXCL2 with expression levels significantly surpassing those observed in SARS-CoV-2 and HKU4 controls, which were positively related to severity in COVID-19 patients." (PMID 40774246, 2025). "Furthermore, CCL5/RANTES is involved in numerous human diseases and disorders, such as viral hepatitis or COVID-19." (PMID 40426971, 2025).
COVID-19 (continued). "This pattern suggests that CCL5 reflects a protective function rather than contributing to pathology in critically ill COVID-19 patients." (PMID 41217548, 2025). "In this study, the relative expression of IRF9, CCL5, IFI6, TGFB1, IL1B, OAS1, and TFRC genes (related to immunity and antiviral activity) was analyzed in upper airway samples from 127 individuals (97 COVID-19 positive and 30 controls) by using a two-step RT-PCR." (PMID 37389217, 2023). "Only 2/6 measures remained different in male and female COVID-19 patients; CD4Temra levels increased further in female COVID-19 patients versus HCW females, whereas CCL5 levels decreased in female and increased in male COVID-19 patients versus female and male HCW, respectively." (PMID 37998327, 2023). "Targeting the CCL5/CCR5 axis can reduce the recruitment of MDSCs from the bone marrow to the lesion site; thus, COVID-19-related immunomodulatory disorders could be improved by targeting this pathway." (PMID 37818369, 2023). "Takahashi assessed immune phenotype in a sample group of COVID-19 patients and concluded that the number of non-classical monocytes and the level of CCL5 were higher in male patients, and activated CD8 T cell numbers were higher in female patients." (PMID 35464985, 2022). "This assumption is confirmed by the fact that a significant increase of the amount of bacterial lipopolysaccharide (LPS), and soluble sCD14 receptor associated with elevated systemic levels of IL-6, TNF-α, CCL5/RANTES and CCL2/MCP-1 was observed in critically ill patients with COVID-19." (PMID 36325402, 2022). "Patients with severe COVID-19 typically have increased serum levels of IL-6, IL-8/CXCL8, CXCL9, CXCL10, TNF-α, MCP1/CCL2, RANTES/CCL5, IL-18, and MIP-1α/CCL3, which promote a sustained pro-inflammatory state that may persist for up to 60 days." (PMID 36289507, 2022). "As for the chemokine CCL5 (RANTES), elevated values have been found in moderate but not severe COVID-19 cases and is considered as a prognostic factor for survival." (PMID 36147602, 2022). "Similarly, high levels of IL-6 and CCL5 (RANTES) as well as viremia and decreased CD8+ T cells are found in terminal COVID-19 patients." (PMID 35062298, 2022). "Six hub genes (FCGR3A, CD69, IFNG, CCR7, CCL5, and CCL4) were involved in regulating immune cells in COVID-19 and HF, which may contribute to the pathogenesis of HF." (PMID 36420258, 2022). "Changes in chemokine levels in peripheral blood of COVID-19 and influenza patients have been addressed by multiple studies, in particular CXCL9, CXCL10, CXCL11, CXCL16, CCL2, and CCL5 were altered in patients as compared to controls, and levels correlated to disease severity." (PMID 35371005, 2022). "We also observed increased levels of CCL5 and CCL3, expressed in NK cells, that interact with the CD191 receptor (CCR1), and whose inhibition potentially suppresses immune hyperactivation in critical COVID-19 patients." (PMID 36443794, 2022). "Findings from mouse models, cellular systems, and samples from patients with SARS-CoV-2-induced COVID-19 have shown massive generation of C5a, CCL chemokines (e.g., CCL2, CCL3, and CCL5), CXCL chemokines (e.g., CXCL9 and CXCL10), and growth factors, i.e., TGFβ, GCSF, GMCSF, VEGF, FGF, and PDGF." (PMID 36430817, 2022). "TH1-like cells from patients with mild COVID-19 exhibited a TH1 polarization state, characterized by upregulation of effector marker genes (PDCD1, CCL5, CXCR2, CCR2, GZMA/B, NKG7, PRF1, IFNG, and CCL4) and genes involved in effector function such as CXCR4, CXCL2, ANXA1, SOCS2 and LTB." (PMID 36119105, 2022). "Amongst T-cell and monocytes/macrophages, some immune-stimulatory or auto-regulatory interactions were seen (CTLA4 or CD28/CD80 or CD86, CCL5/CCR5), but specific epithelial to T-cell interactions in critical COVID-19 were limited to pro-inflammatory ICAM1-mediated interactions." (PMID 33473155, 2021).
COVID-19 (continued). "Spike COVID-19 protein stimulation also leads to increased gene expression of CARD9, and CCL5." (PMID 34571855, 2021). "Patients with severe-to-critical COVID-19 have been shown to have elevated levels of C–C chemokine receptor type 5 (CCR5) ligands including C–C ligand (CCL) 3 (or MIP-1α), CCL4 (or MIP-1β), CCL5 (or RANTES), as well as interleukin (IL) 6 and IL-10." (PMID 33778462, 2021). "Levels of inflammatory cytokines/chemokines, including Eotaxin, G-CSF, Gro-α, CXCL-10, RANTES (CCL5), IL-2Rα, MCP-1, and SCGF-b, were found to be highly elevated in plasma samples from COVID-19 patients within a week post-symptoms as compared to healthy controls." (PMID 34242356, 2021). "The analysis of the plasmatic levels of inflammatory chemokines and cytokines in patients with COVID-19 and MIS-C showed higher levels of IL-6, CXCL8, CCL2/MCP-1, CXCL9/MIG, and CXCL10/IP-10 in MIS-C, whereas CCL5 levels were significantly higher in the COVID-19 group." (PMID 33841438, 2021). "Performing this analysis for the COVID-19 patients demonstrated clear B- and T-cell clusters, defined by expression of TCF7, LEF1 (clusters 0 and 1), CD74, CD79A (clusters 2 and 3), IL7R (cluster 4) and CCL5, NKG7, GNLY (cluster 6)." (PMID 33884369, 2021). "Interestingly, COVID-19 individuals (including PASC, Mild, Severe) show high levels of CCL5, a chemokine that like CCL4 signals through CCR5." (PMID 34262570, 2021). "To investigate the role of cytokines and chemokines in the inflammatory status of COVID-19 and MIS-C, we measured plasma levels of IL-1ß, IL-2, IL-4, IL-5, IL-6, IL-10, TNF-α, IL-17A, IFN-α, IFN-γ, CXCL10/IP-10, CXCL8/IL-8, CXCL9/MIG, CCL5/RANTES, and CCL2/MCP1." (PMID 33841438, 2021). "COVID-19 patients had higher plasma CXCL-10 and CCL5 and marginally higher GM-CSF." (PMID 33272291, 2020). "We show that plasma CXCL2, CXCL10, CCL5, CD40 ligand, IL-10, and GM-CSF concentrations and ELF CXCL1, CXCL10, granzyme B, TRAIL, and EGF concentrations were found in greater concentrations in COVID-19 than in non-COVID-19 ARDS patients." (PMID 33138839, 2020). "Furthermore, peripheral blood levels of CCL5 and IL-10 were increased earlier than IL-6 and IFN-γ in severe COVID-19 patients." (PMID 32766256, 2020). "The mediators CCL3, CCL4, CCL2, CCL5, IL-12, IL-15, IL-1Ra, and PDGF were higher in healthy volunteers, while the mediators CCL11, CXCL10, IL-1b, IL-6, TNF-a, IFN-g, IL-17, IL-9, IL-10, IL-13, FGF-basic, G-CSF, GM-CSF, IL-7, and IL-2 were increased in COVID-19 positive patients." (PMID 37903875, 2023). "While some genes involved in monocyte and lymphocyte migration and function were expressed in the COVID-19(+) TV group (CCL13, CCL8, and CCL20), a greater number of these genes were expressed in the COVID-19(-) PU control group (CCL19, CCL18, CXCL13, CCL4, CCL5, CXCL9)." (PMID 37026002, 2023). "Indeed, platelets of COVID-19 patients seem capable of interacting with SARS-CoV-2 via ACE-2-independent mechanisms and upon contact with the virus, increase the secretion of GPVI, CXCL4 and CCL5 in vitro, as well as surface expression of P-selectin." (PMID 35979369, 2022). "Additionally, there was a significant increase in CCL5 expression in non-surviving COVID-19 patients compared to severe, mild and healthy groups." (PMID 34975885, 2021). "COVID-19 ARDS patients had significantly higher plasma concentrations of CCL5 (p = 0.025) and non-significantly higher plasma concentrations of CXCL2 (p = 0.094), CXCL10 (p = 0.287), CD40 ligand (p = 0.125), IL-10 (p = 0.232), and GM-CSF (p = 0.332) compared with non-COVID-19 ARDS patients." (PMID 33138839, 2020). "Interestingly, as observed in human COVID-19 patients with fatal disease (KO and 1A0) and those with severe disease (6A4) had overall, significantly increased systemic levels of G-CSF, IL-6, IL-10, TNF-α, IL-12 (p40), IL-17A, CCL5, and CCL11 compared to those with moderate disease (6A2 and 1A3)." (PMID 40242753, 2025).
COVID-19 (continued). "Additionally, such increased CCL5, known to stimulate MK ploidy and in turn speed megakaryopoiesis, could explain the increase in MK nucleus size we found in COVID-19 compared with non-COVID-19 lung autopsies." (PMID 35708858, 2022). "Such chemokines are able to recruit polymorphonuclear cells, such as monocytes, memory T cells, NK cells, and neutrophils in the site of infection and pregnant COVID-19 women were characterized by higher levels of CCL4, CCL5, and CXCL2 if compared with pregnant women without infection." (PMID 34326336, 2021). "Further, IL-4, IL-9, CCL5, CCL8, GM-CSF, and PDGF are exclusively induced by SARS-CoV-2 and these differences may explain why multi-organ injury including testicular damage and long-term sequelae is observed in COVID-19 patients and not with influenza virus." (PMID 37200377, 2023).